MELK (maternal embryonic leucine zipper kinase)
Diseases named in the same sentence as MELK in open-access papers (continued):
Sharing a sentence is not in itself a finding about the gene and the disease.
cancer (continued). "To unambiguously determine the effects of MELK loss in cancer cell lines, we applied CRISPR/Cas9 to generate frameshift mutations in the MELK coding sequence." (PMID 28337968, 2017). "As OTS167 exhibits nanomolar potency against cancer cell lines but is unaffected by mutations in MELK, this suggests that OTS167 blocks proliferation by inhibiting another target or targets." (PMID 28337968, 2017). "As part of a project in our lab to characterize genes whose expression is associated with patient prognosis in cancer, we identified MELK as highly-expressed in deadly tumors from multiple cancer types (data not shown)." (PMID 28337968, 2017). "Elevated MELK expression has been identified in a variety of tumors and is associated with poor prognosis in cancer patients." (PMID 26701722, 2016). "MELK is upregulated in various types of human cancer and is known to be associated with cancer progression, maintenance of stemness, and poor prognosis." (PMID 26918358, 2016). "Aberrant regulation and activity of MELK is implicated in a variety of human cancers predominantly because of these properties, but also possibly because of its effect on cancer stem cells." (PMID 25852826, 2015). "MELK expression is also elevated in a variety of cancers and is associated with poor patient survival in breast cancer and astrocytoma." (PMID 25194022, 2014). "Elevated MELK expression has been reported in a variety of solid tumors and has been associated with a poor prognosis for cancer patients." (PMID 25365263, 2014). "According to the TCGA database, MELK alteration (mutation, deletion or amplification) was observed in the range of 1-8% of cases in various types of cancer." (PMID 25365263, 2014). "We found up-regulated the maternal embryonic leucine zipper kinase (MELK), a gene associated to unfavorable survival in MM and known to be associated both to MM and other cancers." (PMID 19753302, 2009). "Besides, the existing literature has reported that MELK is implicated in numerous human cancers, including LUAD." (PMID 38652219, 2024). "MELK is a multifunctional protein implicated in tumor progression in several cancers." (PMID 37377604, 2023). "Knowing that, at least in some cancers, MELK expression is associated with increased proliferation, we hypothesized that an increase in MELK level may lead to a higher rate of proliferation and consequently accelerate wound healing." (PMID 37175795, 2023). "MELK has previously been implicated as an important factor in various cancers." (PMID 37377604, 2023). "Unchecked MELK activity has been implicated in the onset of various cancers." (PMID 37377604, 2023). "MELK is a novel oncogene that has been associated with multiple cellular functions, including carcinogenesis, proliferation, apoptosis, stemness, and metabolism and has drawn much attention in the field of cancer biology, stem cells, and metabolism recently." (PMID 37949877, 2023). "In addition, MELK is known to be overexpressed in multiple types of cancer and is associated with cancer proliferation." (PMID 37175795, 2023). "Furthermore, we used MELK-8A to inhibit the kinase activity of MELK and caused the G2/M phase arrest of cancer cells." (PMID 34671205, 2021). "Additionally, MELK has been implicated in several other cancer-related processes, including cancer stem cell maintenance, chemotherapy resistance, anchorage-independent growth, and reactive oxygen species (ROS)-signaling." (PMID 29417930, 2018).
cancer (continued). "We therefore subjected our MELK-KO and Rosa26 clones to various in vitro and in vivo assays to assess whether MELK loss impairs any cancer-related phenotypes." (PMID 29417930, 2018). "Althrough STRAP and MELK are highly expressed in multiple human cancers, their association in tumor progression and as a therapeutic target is largely unknown." (PMID 29783958, 2018). "The different genetic and chemical tools developed here allow for the identification and validation of any causal roles MELK may play in cancer biology, which will be required to guide future MELK drug discovery efforts." (PMID 28926338, 2017). "Despite a strong association with tumorigenesis, little is known about whether MELK plays a causal role in orchestrating these aggressive cancer phenotypes." (PMID 28926338, 2017). "We clearly demonstrated that the expression of Slug and Snail proteins was decreased in tumors which were treated with OTS167, indicating that OTS167 might lead to loss of cancer stem-like characteristics through inhibition of MELK function." (PMID 26918358, 2016). "MELK increased expression seems to be restricted to cancer tissue while its silencing causes a block of tumour cells proliferation: a result that permits to hypothesize for MELK a role as molecular therapeutic target." (PMID 19753302, 2009). "Moreover, MELK is associated with cancer progression and aggressiveness." (PMID 36674843, 2023). "In addition, MELK overexpression has been associated with poor outcome in some cancers." (PMID 31294536, 2019). "However, it is still unclear whether MELK overexpression in cancer cells has any causal relationship with the CIN phenotype." (PMID 27082996, 2016). "We also discuss the therapeutic potential, limitations, and controversy of MELK inhibitors, and implications in cancer diagnosis and treatment." (PMID 41594935, 2026). "TOPK and maternal embryonic leucine zipper kinase (MELK) together regulate cancer cell proliferation and stem-like properties." (PMID 41362722, 2026). "Maternal embryonic leucine zipper kinase (MELK) is a serine/threonine kinase frequently overexpressed in aggressive cancers, yet the precise mechanisms governing its activation and signaling specificity remain poorly understood." (PMID 42309608, 2026). "Specifically, we assess how MELK knockdown and pharmacological inhibition affect cancer stem cell properties, migration, and invasion; and how MELK overexpression influences metastatic capacity in vivo." (PMID 40076867, 2025). "OTS167, the MELK inhibitor used in this study, has advanced to clinical trials for several cancers and exhibits high selectivity and potency." (PMID 41278210, 2025). "Many recent studies have shown that MELK is highly expressed in various cancers, such as lung, breast, and gastric cancers." (PMID 39871325, 2025). "MELK depletion slowed or stopped the proliferation and invasion of these and other cancer cell lines." (PMID 39871325, 2025). "MELK is a serine/threonine kinase involved in multiple cancer-related processes, including cell cycle regulation, apoptosis suppression, and stem cell maintenance." (PMID 40564876, 2025). "Maternal embryonic leucine zipper kinase (MELK) has emerged as a potential driver of aggressive cancer phenotypes and a promising therapeutic target in TNBC." (PMID 40076867, 2025). "Treatment with the MELK inhibitor OTSSP167 significantly reduced mammosphere formation efficiency in cancer stem cell populations (CD44+/CD24− and ALDH+) compared to untreated controls." (PMID 40076867, 2025).
cancer (continued). "In recent years, increasing evidence has confirmed that MELK serves as an oncogene in multiple cancer types, including colorectal cancer, breast cancer and lung cancer." (PMID 38970074, 2024). "Of interest, the inhibitory effect of MELK inhibition has been more effective on cancer stem cells than on GBM cells." (PMID 38167429, 2024). "Recent years have witnessed interest and confusion in MELK as a potential target for cancer therapy due to its overexpression in multiple cancers." (PMID 39355119, 2024). "MELK was also ranked #11 in the CIN25 signature genes whose overexpression is characteristic of cancer cells exhibiting chromosomal instability." (PMID 39355119, 2024). "Controversies concerning MELK functions in cancer development still remain, but recent advances demand better understanding of MELK functions at the molecular and individual cell levels." (PMID 39355119, 2024). "The findings of Wang and colleagues highlight the importance of experimental design and technical considerations in cancer target validation and reconcile some of the disparities in the current literature regarding MELK dependency in cancer progression." (PMID 37377604, 2023). "MELK knockdown by siRNA or MELK inhibition by inhibitors showed a strong growth-inhibitory effect on cancer cells." (PMID 37377604, 2023). "This can be exemplified by the significance of MELK, which was indicated as a potential drug target, but it was shown dispensable for cancer cell viability when CRISPR-mediated MELK knockout experimental models were applied." (PMID 37031274, 2023). "According to the microarray and TCGA datasets study, MELK (maternal embryonic leucine zipper kinase) expression is higher in many cancer cells and tissues than their counterparts." (PMID 35880695, 2023). "Previous studies reported that MELK was significantly upregulated in multiple human cancers and correlated with poor prognosis." (PMID 37949877, 2023). "According to research, MELK has been recognized as an efficient therapeutic target and prognostic factor in the treatment of cancer." (PMID 35880695, 2023). "Maternal–fetal leucine zipper kinase (MELK) is involved in many cancer-related processes, including chemoresistance, stem cell turnover, and tumor growth." (PMID 37008632, 2023). "According to a study, this MELK gene was found to possess therapeutic drug-like properties due to its role in cell proliferation and triggering of cell cycle arrest in different cancer types." (PMID 36900109, 2023). "At the protein level, MELK is hyperphosphorylated and reaches maximal activity during the M phase of the cell cycle in human cancer lines and embryonic cells." (PMID 37175795, 2023). "In vitro and in vivo studies have spotlighted MELK as a central driver of both cancer progression and relapse, thus highlighting its prominence as a therapeutic target." (PMID 37509358, 2023). "Object: Maternal embryonic leucine zipper kinase (MELK) is involved in the development and progression of various cancers." (PMID 35511171, 2022). "The relationship between MELK and survival in the 18 cancer types was evaluated using the GEPIA database, using both overall survival (OS) and disease-free survival (DFS)." (PMID 35511171, 2022). "In this study, we showed that the gain of MELK gene copies was a common alteration in cancers of the breast, endometrium, and ovary (4.7%-50%)." (PMID 35749404, 2022). "To explore the possible roles of MELK in carcinogenesis, we compared its expression between tumor and normal tissues in 33 types of human cancer in TCGA database." (PMID 35693941, 2022).
cancer (continued). "It has been reported that MELK is highly upregulated in various types of human cancer according to TCGA dataset and that elevated MELK expression is correlated with poor prognosis of cancer patients." (PMID 35693941, 2022). "Collectively, the data from TCGA, CCLE, and AA-enriched samples showed that MELK is highly expressed in BLBC tumors compared with all types of cancers." (PMID 35749404, 2022). "Pan-cancer evaluation of MELK expression also revealed the greatest expression in BLBC tumors (BRCA-Basal) compared to all other tumors." (PMID 35749404, 2022). "Here, we evaluated the relationship between MELK levels and patient outcomes in a variety of cancers." (PMID 35511171, 2022). "Oncomine analysis of cancer vs. normal tissue showed that MELK was significantly overexpressed in HCC tissue in different datasets." (PMID 35511171, 2022). "More and more studies have found that MELK is involved in the occurrence of cancer and cell metabolism by regulating the cell division cycle." (PMID 36440267, 2022). "MELK has been reported to play key roles in several types of human cancers and predict poor prognosis." (PMID 35693941, 2022). "We first conducted pan-cancer analysis of the expression of MELK by analyzing RNA-seq data from TCGA database and GEPIA database." (PMID 35693941, 2022). "To compare MELK expression across various cancers, we utilized RNA-Seq data in pan-cancer samples of The Cancer Genome Atlas (TCGA) and analyzed MELK expression in 33 types of human cancers (n = 10,967)." (PMID 35749404, 2022). "For OS and RFS, increased expression of MELK indicated poor prognosis in HCC among all cancer types." (PMID 35693941, 2022). "Recent studies have found that APE1 is highly expressed in a variety of cancers, and knockdown of MELK expression decreases cancer cell proliferation and induces apoptosis." (PMID 36523974, 2022). "In recent years, many studies have reported that MELK has potential carcinogenic effects and plays a key role in maintaining the stemness of cancer cells." (PMID 35440604, 2022). "We initially examined MELK expression in 18 different cancer types, finding that MELK levels were significantly elevated in all 18 cancers in comparison with normal tissue." (PMID 35511171, 2022). "Here, we first analyzed MELK levels in a variety of cancers using data from the TCGA, followed by verification using GEPIA." (PMID 35511171, 2022). "We report widespread and consistent changes in alternative splicing of cancer-associated genes including CENPE, ESCO2, CKAP2, MELK, ASPH and CD164 in both HeLa and PC3 cells." (PMID 33846420, 2021). "The positive MELK staining was primarily located in the cytoplasm of cancer cells, and the expression in OSCC was significantly higher than that in normal mucosa tissues." (PMID 33962400, 2021). "Nevertheless, six studies reported that exogenous MELK expression was able to rescue the effect of growth suppression, tumorsphere suppression, or cell death by RNAi-mediated MELK knockdown in cancer cells." (PMID 34285339, 2021). "MELK is reported to be involved in multiple cellular events in tumorigenesis and malignant progression of human cancers by phosphorylation and regulation of several signaling molecules, such as NF-κB and mTOR." (PMID 33931086, 2021). "Maternal embryonic leucine zipper kinase (MELK) is frequently overexpressed in cancer, but the role of MELK in cancer is still poorly understood." (PMID 34550356, 2021). "Mechanistic investigation indicated that PCDHB17P acted as a cancer-promoting competing endogenous RNA (ceRNA) by binding miR-145-3p and upregulating MELK." (PMID 34350110, 2021). "Moreover, OTS167 was recently reported to inhibit BUB1 and Haspin kinases as well as MELK, reducing phosphorylation at histones H2A and H3 and causing mislocalization of Aurora B, which resulted in abolishment of the mitotic checkpoint and abortion of cytokinesis in cancer cells." (PMID 34285339, 2021).
cancer (continued). "This evidence strongly suggests that MELK, especially its kinase activity, is necessary for the proliferation of cancer cells." (PMID 34285339, 2021). "The most upregulated kinases included Protein Kinase, Membrane Associated Tyrosine/Threonine 1 (PKMYT1) (in 17 cancers), and Maternal Embryonic Leucine Zipper Kinase (MELK) (in 16 cancers)." (PMID 33801837, 2021). "MELK plays a prominent role in cell cycle control, cell proliferation and cancer treatment resistance and is a good candidate for potential anti-cancer therapies." (PMID 33431809, 2021). "It has been proven that the proliferation of multiple cancer cell lines depends on maternal embryonic leucine zipper kinase (MELK) through RNAi or small-molecule targeted drugs." (PMID 34261433, 2021). "The role of maternal embryonic leucine zipper kinase (MELK) in cancer is varied, including proliferation, apoptosis, epithelial transformation, and metastasis." (PMID 34350110, 2021). "Given the preferential upregulation of MELK in various cancer types, small molecule inhibitors of MELK have been developed and are currently in Phase I clinical trials for metastatic breast cancer." (PMID 33801837, 2021). "Maternal embryonic leucine zipper kinase (MELK) has been identified as a promising therapeutic target in multiple cancer types." (PMID 33962400, 2021). "Recent studies have shown that treatment with OTS167 drastically suppresses the growth of various MELK-overexpressing cancer cell lines, including breast, lung, prostate, AML, gastric, kidney, and ovarian cancers." (PMID 34285339, 2021). "According to the results, we found that positive MELK staining was primarily located in the cytoplasm of cancer cells, and its expression was significantly higher in OSCC versus normal mucosa tissues." (PMID 33962400, 2021). "We therefore downloaded expression data and copy number status of MELK from the Cancer Cell Line Encyclopedia (DepMap release 21Q1) and tested which genes are essential in cells overexpressing MELK from RNAi screens." (PMID 34550356, 2021). "TCGA data from GEPIA and starBase Pan-Cancer Analysis Platform both disclosed higher expression of MELK in LUAD and LUSC tissues." (PMID 33931086, 2021). "The oncogenic properties of MELK make it to be a key functional regulator of drug resistance in several lines of cancers." (PMID 32581798, 2020). "Accumulating evidence has shown that MELK was highly expressed in various kinds of human cancer and this expression was correlated with the development and progression of malignancy tumors." (PMID 32047721, 2020). "Mechanistically, the activity of FoxM1 is regulated by MELK kinase in various cancer cells; however, the contribution of MELK-FoxM1 signaling in the process of DOC resistance acquisition in TNBC is never deeply investigated." (PMID 32581798, 2020). "More and more studies have indicated that MELK expression is higher in numerous cancer cells and MELK can drive the most tumor development." (PMID 33520717, 2020). "The MELK gene is overexpressed in different types of cancers, including ‘triple negative’ breast cancer (TNBC), the most aggressive form of this type." (PMID 32946434, 2020). "It is worth noting that this finding doesn't exclude the possibility that MELK can also function in cancer stemness with its cell cycle dependent expression pattern." (PMID 31380279, 2019). "To corroborate the staining results regarding cancer stem-like features in GSCs, we found robust expression of MELK, EZH2, and NF-κB in GSCs sorted from GBM cell-line, U87 and primary human GBM tissues, compared with control cultures." (PMID 31380279, 2019).